TLR3 (toll like receptor 3)
Diseases named in the same sentence as TLR3 in open-access papers (continued):
Sharing a sentence is not in itself a finding about the gene and the disease.
infection (continued). "Our results showed that the expression levels of TLR3, IFIH1, and IRF7 were increased after infection in resistant chickens; and expression levels of IRF7 were higher in resistant H5N1-infected chickens than in susceptible H5N1-infected Ri chickens." (PMID 34991196, 2022). "In contrast, the miR29b-1* mimic still efficiently reduced AdV-C5 infection when the dsRNA sensor MDA5 or TRIF, the downstream effector of the dsRNA sensor TLR3, were knocked down by siRNAs." (PMID 35891387, 2022). "P/V/F mutant infection upregulates expression levels of OAS2 by ~40 fold and TLR3 expression by ~15 fold, respectively, with only modest gene expression changes seen with the WT infection." (PMID 35631014, 2022). "As a DNA virus, PRV can establish long-term infection by evading cGAS-STING- and TLR3-induced antiviral innate immune responses." (PMID 35891444, 2022). "During the infection process, HHV DNA can be recognized by DNA sensors TLR3/9, STING and IFI16, which are present in the endosome, cytoplasm and nucleus, respectively." (PMID 35337341, 2022). "Classically unrelated effects from TLR3 during DENV infection have been shown, such as its role in microglial migration, through the dsRNA recognition pathway during infection." (PMID 35632732, 2022). "The necroptosis pathway is triggered during pathogen infection and cellular damage by activation of specific death receptors including TNF receptor, FAS, and TLR3." (PMID 36619743, 2022). "The up-regulation of TLR3, PI3K and the down-regulation of TRAIL, and RIP1 were noticed in a time-dependent manner in both infection groups." (PMID 35234615, 2022). "When infected with RV 16, the expression levels of TLR3, RIG-I, and MDA5 mRNA and protein tended to increase over time in both groups of epithelial cells and reached peak levels at 48 h post-infection, showing a similar pattern to that of RV16 replication." (PMID 36341332, 2022). "Leukocytes expressed TLR2, TLR3, TLR4, TLR6, and TLR7 can interact with RSV and promote immune responses following infection." (PMID 35308390, 2022). "SC were primed with poly I:C, a dsRNA mimic that is shown to activate TLR3, RIG-I, and MDA5 pathways, 24 h before infection." (PMID 36713156, 2022). "The results showed that the expression levels of TLR3, IRF7, IFN-α/β and the corresponding downstream antiviral factors OAS, PKR and Mx were all upregulated in the SPF chicken ILP cells at 8 h post-infection (hpi) and 12 hpi." (PMID 35215986, 2022). "TLR3, 7 and 9 are also expressed on CD8+ T-cells where their expression can be modulated by infection." (PMID 36714124, 2022). "As expected, TLR3 and TLR7 mRNA levels were increased up to 1.4-fold in GR1−/− and G+/−GR1−/− cell lines after HCoV-OC43 infection compared with infected wild-type cells." (PMID 35897807, 2022). "In particular, genes that are known to activate NF-kappaB, e.g., TLR1, TLR3, TRAF5 and CD14, showed increased expression over infection time." (PMID 36544767, 2022). "RIG-I, TLR3, and MDA5 are well-conserved cytoplasmic PRRs that detect viral RNAs during infection and activate the type I IFN-mediated antiviral immune response." (PMID 33407600, 2021). "Upon infection (primary or reactivation) with HSV-1, activated TLR3 signaling leads to production of IFNs which then initiate an adaptive immune response." (PMID 34199501, 2021). "In accordance with this, our results showed that TLR3, RIG-1, MDA-5, and IRF7 were activated during GNAstV infection." (PMID 33647718, 2021). "Infection by SARS-CoV-2 induces the release of a proinflammatory cytokine such as IL-1β through activation of TLR2 (toll-like receptor 2), TLR3, or TLR4." (PMID 34306796, 2021). "Overall TLR3+/- and MDA5+/- mice have distinctive tissue specific expression of IFN-I inducers TLR3 and MDA5 and unique tissue-specific IFN-I responses after infection with the same virus." (PMID 34804036, 2021).
infection (continued). "Taken together, this data suggested that activation of the NRF2 pathway in LgyLRV1+ infection resulted in the control of the NF-κB pathway and thereby limited the detrimental effect of LRV1/TLR-3 axis." (PMID 33765083, 2021). "Compatible with the data obtained from analyzing the TRIF KD and KO, both TLR3 and TLR4 proved to be required for optimal production of IL-6 following infection with L. pneumophila." (PMID 34280250, 2021). "The results of the present study demonstrated that the innate immune sensing of rNDV-H5 is mediated by TLR3, MDA5, and LGP2 receptors during early infection of CEFs and TOCs, resulting in the induction of IFNβ expression in CEFs." (PMID 34358174, 2021). "After 48 h of infection, we observed a predominant induction of both TLR7 and TLR3 expression (p < 0.001; Student’s t-test)." (PMID 34576716, 2021). "As poly(I:C) selectively activates TLR3, we attempted to construct an oncolytic vector virus with the capacity to activate the TLR3-IRF3 pathway after infection." (PMID 34553028, 2021). "Increased expression levels of TLR3 and/or TLR7, RIG1, and MyD88 genes were detected in response to infection, resulting in the transcriptional upregulation of IFN-λ1 in both ALI-PREC cultures and tracheal epithelia." (PMID 34935443, 2021). "Because the magnitude of the effect of the gene KO was comparable across these four TLRs, we posit that TLR2, TLR3, TLR4, and TLR5 are equally important in the macrophage response to L. pneumophila at least at the early stages of infection." (PMID 34280250, 2021). "To confirm that the effect of famotidine on the TBK1/IRF3 pathway is through TLR3-dependent signaling, we treated Caco2 cells with the TLR3 inhibitor CU-CPT 4a, which was added at the time of infection." (PMID 34214498, 2021). "In the current study, following infection of rohu with A. invadans, TLR2, TLR3, TLR4 and TLR9 were downregulated." (PMID 33177569, 2020). "Infection with IAV PR8 resulted in a 40- and 15-fold increase in RIG-I and TLR3 mRNA levels, respectively, over mock-infected cells." (PMID 32235406, 2020). "MDA5- and TLR3-dependent signaling pathways can induce large amounts of IFN-I and ISGs to resist DTMUV infection." (PMID 32641107, 2020). "In the present study, we found that miR-148a-5p is a target miRNA of TLR3 that is significantly decreased both in DEF cells and DEF-Exo following DTMUV infection." (PMID 31947624, 2020). "All of these results suggest that after DTMUV infects, the high level of TLR3 can both increase the expression of IFN-β and decrease the level of miR-148a-5p to resist DTMUV infection." (PMID 31947624, 2020). "Among the PRRs expressed in brain tissues, DTMUV infection increased the mRNA levels of RIG-I, MDA5, but decreased TLR3 significantly." (PMID 32351903, 2020). "Recent data have demonstrated that infection by helminths of the Schistosoma genus affects the expression of several nucleic acids sensors, such as AIM2, TLR3, and TLR75,31,32." (PMID 32404867, 2020). "During infection with ssRNA viruses, key PRRs such as MDA5, RIG-I, and TLR3 will recognize dsRNA generated during viral replication." (PMID 32635205, 2020). "NDV infection increased the expression of toll like receptor TLR3, TLR7, MDA5, IFN-α, IFN-β, IFN-γ, IL-8, and CXCLi1 in the testes of NDV-infected roosters at 5 days post-infection (dpi)." (PMID 32600413, 2020). "Then we compared the expressions of RLRs and TLRs after infection, and found that the expressions of MDA5 were much higher than RIG-I, while the expressions of TLR3 was much higher than those of TLR2 and TLR4." (PMID 31947624, 2020). "Human IV infections, such as H1N1 and H3N2, increase the expression of TLR family members, including TLR3, 7, 8, and 9; however, TLR2 and 4 are suppressed in this setting." (PMID 32689931, 2020).
infection (continued). "Upon infection with MTB, TLR3 knockout mice showed diminished IL-10 levels and increased Il-12 production, higher Th1-cell counts in the spleen and a lower mycobacterial burden; thus, hinting toward a detrimental effect of TLR3 activation." (PMID 32033104, 2020). "Among the PRRs expressed in the spleens, DTMUV infection increased the mRNA levels of RIG-I, MDA5, and TLR3 significantly." (PMID 32351903, 2020). "Specifically, wild-type poliovirus infection of human neuroblastoma cells (SK-N-SH) delayed the innate immune response by decreasing expression of TLR3 and MDA5 for 8 h post infection." (PMID 32328043, 2020). "Previous study showed that TLR3 and TLR5 were upregulated at 24, 48 and 72 h post-infection in A549 pulmonary epithelial cells treated with Mtb, and the expression of neutrophil TLR2 is also increased in PTB patients." (PMID 32811479, 2020). "Since only TLR3 and 7 directly detect IAV during infection in birds, we will focus on these TLRs in the next two sections." (PMID 32477965, 2020). "Compared with control, important adaptor factors of the TLR3 and MDA5 pathways (e.g., TRIF, IRF7, IPS-1, and NF-κB) were up-regulated in TLR3- and MDA5-over-expressing cells following DTMUV infection." (PMID 31947624, 2020). "One study found that, through infection of THP-1- and CD14-positive primary human monocytes, HHV8 upregulates the TLR3 pathway and induces TLR3-specific cytokines and chemokines, including beta 1 interferon (IFN-β1) and CXCL10 (IP-10)." (PMID 33519292, 2020). "Next, the role of TLR3 in the regulation of type III IFN induction upon CVB3 and PV1 infections was investigated." (PMID 33203755, 2020). "Ultimately, Npro’s antagonism of TLR3-, RIG-I-, and IRF3-mediated apoptotic responses serves as another mechanism of CSFV immune evasion, likely contributing to the establishment of infection and host persistence." (PMID 33328306, 2020). "Infection of human lung A549 epithelial cells with an HEV1 strain, derived from a patient’s stools, confirmed the involvement of TLR3 in dsRNA recognition." (PMID 32731452, 2020). "To investigate the mRNA of PRRs, IFNs and ISGs in the spleens of H5N6 viruses infected geese, we quantified the mRNA expression of TLR7, TLR3, RIG-I, MDA5, IFN-α, IFN-γ, Mx, and OASL at 12 hours and 3 days post-infection with the two H5N6 viruses." (PMID 32046051, 2020). "Involvement of TLR3 in responding to VACV infection has been demonstrated and appears to drive aspects of immunopathology of this infection in mouse models, even though lower levels of virus replication are observed in TLR3−/- mice." (PMID 33092186, 2020). "Numbers of subepithelial TLR3+, MDA5+, and RIG-I+ cells were significantly increased on day 4 after infection in asthmatic patients (P = .002.02, and .004, respectively)." (PMID 29698627, 2019). "During infection, viral RNA detection by sensors such as RIG-I or Toll-like receptor 3 (TLR3) results in the induction of type I or type III IFNs as well as of proinflammatory cytokines." (PMID 31597767, 2019). "In comparison to the control uninfected group, mRNA expression levels of TLR3, TLR4, TLR7, MyD88, RIG-1 and NF-κB p65 in the control infected group were prominently increased on days 3 and 7 post-infection (all P < 0.01)." (PMID 31551774, 2019). "TLR3, TLR7, and TLR9 are known to be important host factors involved in restricting EV71 infection in diverse infection models in vivo and in vitro." (PMID 31730654, 2019). "Numbers of subepithelial TLR3+ and RIG-I+ cells during infection were related to viral load and rhinovirus-induced clinical illness severity in vivo." (PMID 29698627, 2019). "Whereas the protein levels of TLR3 and TLR4 declined at 12 h and 24 h, respectively, after infection by wild-type HCMV, they were barely affected by infection with HCMVΔUS7-16." (PMID 31604943, 2019).
infection (continued). "Infection with S. Typhimurium and S. Dublin led to a significant downregulation of TLR2, TLR3, TLR4, TLR5, and TLR7 in chicken macrophages HD11, whereas only a slight downregulation of TLR3 and TLR7 genes was observed in the S. Gallinarum infection group." (PMID 31998655, 2019). "Compared with the normal control group, the expression levels of all proteins (TLR3, TAK1, TBK1, IRF3, and IFN-β) were increased after infection with influenza virus." (PMID 31975996, 2019). "Infection also results in enhanced expression of several IFN stimulated genes, especially IFNA1, IFNB1, and TLR3 transcripts." (PMID 31474994, 2019). "Increased numbers of subepithelial IFN-α+, TLR3+, and RIG-I+ cells during infection are related to greater viral load/illness severity." (PMID 29698627, 2019). "The CH strain downregulated TLR3 and TLR7 during the early stage of infection (24 and 36 hpi); this downregulation was most obvious at 36 hpi." (PMID 29700351, 2018). "Our in vivo findings have shown that C. muridarum infected TLR3-/- mice generated in both the 129S1 and C57BL/6N backgrounds are defective in the synthesis of IFN-β on day 6 and 8 of infection, respectively." (PMID 29624589, 2018). "Production of IFN-β by both TLR3 and RIG-I induced signaling would be expected to further increase expression of PD-1 ligands later in infection." (PMID 30559738, 2018). "Silencing of TLR3 in mouse and human primary immune cells impaired the activation of IFN-β upon EV-A71 infection, thus reinforcing the importance of the TLR3 pathway in defending against EV-A71 infection." (PMID 30563052, 2018). "In an infection model for influenza virus, type I IFN initiates an anti-influenza virus effect through an RIG-I/TLR3/NLRP3 dependent pathway." (PMID 30013955, 2018). "Previous studies have shown that mRNA levels of TLR3, 7/10 of goat PBMC are upregulated by PPRV vaccine virus Sungri/96 strain infection and these control both the sensing and the proinflammatory and antiviral responses to PPRV." (PMID 30012212, 2018). "TLR3 also induces type I IFN during WNV, ATMUV, and ZIKV infections; however, the NS1 protein of WNV can suppress this way by inhibiting the transcription of IRF3 and activation of NF-κB cytokine transcription, resulting in low levels of inflammatory factors." (PMID 29888293, 2018). "Our results showed that TLR3 knockdown in BMMs significantly impaired the expression of IFN-β and IL-6 cytokine genes upon EV-A71 infection." (PMID 30563052, 2018). "The transmembranar TLR3, and the cytosolic helicases MDA5 and RIG-I PRR mRNA expression was increased in infected keratinocytes after 24 and 48 h of infection." (PMID 30450338, 2018). "Loss-of-function analyses further confirmed the importance of TLR3 and its downstream regulators, Trif and TAPE, in detecting EV-A71 infection and signaling to type I IFN activation." (PMID 30563052, 2018). "UNC93B1 can facilitate trans-location of TLR (TLR3, TLR7 and TLR9) from the endoplasmic reticulum to the Golgi and mediates the host immune responses to infection with murine cytomegalovirus, as well as several intracellular protozoan parasites." (PMID 29530077, 2018). "The ELISA results showed that silencing of Trif or TAPE impaired TLR3-mediated cytokine production of IFN-β, RANTES, and IP-10 during EV-A71 infection." (PMID 30563052, 2018). "In the spleen, the expression level of TLR3 was downregulated in response to SW8 infection, yet upregulated following infection with ZH283." (PMID 28676793, 2017). "Inflammatory response genes, such as NOS2, IL6 and TNFRSF1B, were up-regulated while some positive regulation of inflammatory response genes, such as TLR3, STAT5 and LRRC32, were also elevated post-infection with IBDV." (PMID 28486945, 2017). "CSFV Shimen infection results in a significant induction of TLR2, TLR4, and TLR7, but decreased of TLR3." (PMID 28751780, 2017).
infection (continued). "In this study, we focused on the stimulatory activity of B. abortus RNA, as well as the role of TLR3 and TLR7 in cell signaling pathways and host protection against infection." (PMID 28167945, 2017). "Remarkably, the expression levels of TLR3 and S1PR1 were upregulated in the brain following infection with SW8 and ZH283, yet showed different expression patterns in lymphoid tissues." (PMID 28676793, 2017). "To investigate the effects of CCM111 on infection-mediated signaling, we further investigated the effects of CCM111 on the TLR2, TLR3 and TLR4 signaling pathways using stable cells and luciferase reporter assays." (PMID 28687744, 2017). "The expression of TLR3, TLR7, IL-6, IFN-alpha, IFN-gamma, MHC-I and MHC-II, except for IL-8, were also greater in CEFs than in DEFs in response to infection to both viruses or treatment with poly(I:C)." (PMID 26975566, 2016). "Further, IECs significantly increased expression of two nucleic acid sensing PRRs, TLR3 and IFI16, following infection with C. concisus BAA-1457, which is suggestive of bacterial lysis within the host cell." (PMID 27677841, 2016). "For instance, IBV 2575 AT infection activated multiple PRR genes, including IFIH1, TLR1LA, TLR2-2, TLR3, TLR4, TLR7, and TLR15." (PMID 27876864, 2016). "After 24 h of infection, IAV induced RIG-I expression was decreased by 87 % while TLR3 was decreased 79 % in cells from smokers." (PMID 27604339, 2016). "Collectively, our results demonstrate that pneumococcal RNA is a stimulus for the TLR3/TRIF pathway, which is required to induce the production of IL-12p70 by DCs during infection with pneumococci, a pathway that can be primed by IAV coinfection." (PMID 26956584, 2016). "The expression of PRRs involved in sensing nucleic acids (TLR3 and IFI16) and the NOD-like receptor NLRP9 increased following infection." (PMID 27677841, 2016). "We also observed that up-regulation of hepatic expression of 2OAS-1, RIG-I, TLR3, TLR7, and CXCL10 mRNAs was found as early as 7 days after infection and coincident with serum HCV RNA appearance." (PMID 27788241, 2016). "TLR2, combination 1 (TLR3 ON and SHP2_T OFF), and combination 2 (TLR3, MKP_T ON and SHC_T OFF) mostly lead to the infection-free attractor (...110...) similar to the uninfected scenario." (PMID 26660865, 2015). "Conversely, a number of adaptor genes involved in TLR3 signaling such as TRIF, TRAF6 and RIP1 were up-regulated within 24–48 hours of infection." (PMID 25826356, 2015). "Other studies have also reported this differential regulation of TLR3 and TLR7 following infection with a classical strain of IBDV." (PMID 25505077, 2015). "TLRs can sense the infection of RNA viruses, TLR7 binds with the ssRNA derived from viruses like influenza virus and TLR3 senses dsRNAs." (PMID 26206138, 2015). "We detected the expression of PRRs (Rig-1, Mda5, and Tlr3) in the brains and spleens of ducks infected with DTMUV during the early post infection period." (PMID 26005441, 2015). "Transcription of TLR3 and TLR9 was down regulated in the later stages of infection (comparing Groups 1 and 2)." (PMID 26465878, 2015). "While freshly isolated B cells and DCs express little LLT1 mRNA, transcript levels are augmented following infection with viral pathogens (e.g., influenza, HSV-1, EBV, HIV) or TLR agonists (i.e., TLR-3, -4, -7, -8, -9), in particular CpG DNA treatment." (PMID 24917862, 2014). "Our data demonstrate that sELR1 and IFNβ are up-regulated when TLR3 is activated and those cells in which TLR3 is activated show enhanced resistance to EIAVUK3 infection." (PMID 25106750, 2014). "We observed increased phosphorylation of IRF3 in HEK293-TLR3 cells compared to HEK293-NULLs likely due to the convergence of TLR3-dependent and RIG-I-dependent signaling events in response to WNV at late times post-infection." (PMID 25127040, 2014).